RNU6-191P (RNA, U6 small nuclear 191, pseudogene)
Gene: Small nuclear RNA gene on chromosome 4 (64,397,694 to 64,397,787, reverse strand). Ensembl gene ENSG00000252104.
Homologues: Orthologues: chimpanzee U6 (100% identical), macaque U6 (79% identical), dog U6 (77% identical), pig U6 (73% identical), rabbit U6 (71% identical). Paralogues in human: RNU6-1029P (83% identical), RNU6-44P (82% identical), RNU6-890P (82% identical), RNU6-1124P (81% identical), RNU6-38P (81% identical), RNU6-49P (81% identical), RNU6-774P (81% identical), RNU6-842P (81% identical), RNU6-1011P (80% identical), RNU6-1117P (80% identical), RNU6-1189P (80% identical), RNU6-1237P (80% identical), and 1286 more.